KAT2A (lysine acetyltransferase 2A)
Diseases named in the same sentence as KAT2A in open-access papers (continued):
Sharing a sentence is not in itself a finding about the gene and the disease.
tumor (continued). "Various studies have shown that lysine acetyltransferase 2A (KAT2A), E2F transcription factor 1 (E2F1), and ubiquitin conjugating enzyme E2 C (UBE2C) genes regulated the proliferation and migration of tumor cells through regulating the cell cycle." (PMID 36292703, 2022). "For example, lysine acetyltransferase 2A (KAT2A) is known to succinylate H3K79 and to promote tumor cell proliferation." (PMID 36359005, 2022). "As a result of the TCGA pan-cancer transcriptome data, the expression levels of KAT2A and E2F1 were significantly up-regulated in 16 and 20 kinds of tumor tissues compared with normal tissues, respectively." (PMID 36292703, 2022). "Though the studies of KAT2A‐mediated histone succinylation at lysine residues in the nucleus are at an early stage, specific data demonstrate that it may be a crucial part in the development of diseases such as tumours, human pancreatic ductal adenocarcinoma (PDAC) and hepatitis B virus." (PMID 34160884, 2021). "KAT2A, SP140 and BRD9 protein expression was higher in tumor tissues, and SMARCA2, BRPF3, KAT2B and EP300 protein expression was lower in the tumor tissues." (PMID 34149798, 2021). "For example, lysine acetyltransferase 2A (KAT2A, also known as GCN5) can specifically succinylate histone H3K79 to promote tumor development." (PMID 32766790, 2020). "It is apparent that KAT2A and MYC are indeed overexpressed in PRAD tumours compared to normal prostate tissue." (PMID 28592290, 2017). "Notwithstanding these open questions, the tumor cell death elicited by KAT2A/SRSF11 inhibition—selectively disabling HR without perturbing NHEJ—positions this pathway as a precision therapeutic vulnerability in radiation oncology." (PMID 41198615, 2025). "Additionally, we experimentally validated the biological roles of KAT2A by examining its effects on LUAD cell line behavior and tumor growth in xenograft models." (PMID 41225436, 2025). "These multi-omics analyses demonstrated significantly increased KAT2A expression in primary tumor tissues relative to adjacent normal tissuess." (PMID 41225436, 2025). "We observed that metastatic burden was dramatically reduced in the absence of KAT2a expression compared to control, while primary tumor growth showed only a small reduction compared to control." (PMID 36732635, 2023). "Interestingly, using a pan-cancer dataset to study the expression of the succinylation regulators CPT1A, KAT2A, sirtuin 5 (SIRT 5), and SIRT7 showed that especially KAT2A was up-regulated in all types of tumours compared to healthy controls." (PMID 38213532, 2023). "Although succinylation can be installed non-enzymatically using succinyl-CoA as a cofactor in vitro, it has been revealed that succinylation of H3K79 can be catalyzed by lysine acetyltransferase 2A (KAT2A, also known as GCN5) in cells to promote tumor cell proliferation and tumor development." (PMID 35547393, 2022). "KAT2A and PPARD showed different expressions between tumor stage and grades." (PMID 36476410, 2022). "Failure of aKGDH to enter the nucleus or mutations in Y645 in KAT2A to nonfunctional alanine prevents the succinylation of H3K79 and inhibits tumor cell proliferation." (PMID 36359005, 2022). "In both tumor types we found correlations between high ADAM12 expression and lower KAT2A levels." (PMID 30753595, 2019). "When α-KGDH complex does not enter the nucleus, or KAT2A gene expression is reduced, inhibition of tumor cell proliferation and tumor growth was observed." (PMID 31881713, 2019). "Our recent studies reported that KAT2A can also function as a histone succinyltransferase by directly transferring the succinyl group from succinyl-CoA to histone H3 lysine 79 (H3K79), which is important for the regulation of gene expression in tumor cells." (PMID 30109122, 2018).
tumor (continued). "However, tumors eventually overcome KAT2A/KAT2B degradation, suggesting that more complete KATA2A/KAT2B degradation may be necessary for tumor regression or that SAGA inhibition may require combinatorial therapies." (PMID 38820154, 2024). "A study demonstrates that KAT2A could act as a histone succinyltransferase from succinyl-CoA directly to histone H3 lysine 79 (H3K79) from a molecular perspective, which is important for the regulation of gene expression in tumor cells." (PMID 38835015, 2024). "In line, overexpression of wildtype Tm4sf1 in Zdhhc20 silenced 4T1 tumor spheroids failed to rescue STAT3 phosphorylation, KAT2A gene and protein expression in the presence and absence of extra palmitate." (PMID 41826695, 2026). "Imaging and size analysis revealed significantly reduced spheroid growth in the KAT2A-targeting sgRNA group compared to the NTC group, although complete tumor progression arrest was not achieved." (PMID 40140561, 2025). "ACSS2, traditionally associated with acetyl-CoA synthesis, facilitates histone lactylation via lysine acetyltransferase 2A (KAT2A), also known as general control non-depressible 5 (GCN5), to promote tumor immune evasion, while GTPSCS drives lactyl-CoA production to support gliomagenesis." (PMID 40867622, 2025). "Furthermore, KAT2A and PPARD showed different expression levels based on the tumor stage, while TCF7L2 expression showed no significant change between different tumor grades." (PMID 36476410, 2022). "Only for five genes, namely KAT2A, SMARCA4, BAZ1A, ATAD2 and TRIM28, we observed consistently higher levels and for two genes—KAT2B and SMARCA2—lower levels, respectively, regardless of the tumor type." (PMID 35049055, 2022).
cancer (46 papers, 2015 to 2026). A tumor composed of atypical neoplastic, often pleomorphic cells that invade other tissues. "KAT2A HAT activity for histone H3 modifications has been confirmed to be associated with the poor prognosis of many cancers." (PMID 35449131, 2022). "Our results unveil a tight connection between TFIIH and KAT2A that controls higher-order chromatin structure and gene expression and provide new insights into transcriptional misregulation in a cancer-prone DNA repair-deficient disorder." (PMID 30894545, 2019). "Notably, KAT2B co-acetylates PLK4 with KAT2A at K45/K46 sites, suppressing its kinase activity to prevent centrosome amplification leading to cancer-associated chromosomal instability." (PMID 40495188, 2025). "We have recently shown that KAT2A high expression significantly associates with cancer stemness across distinct types of solid tumors, although mechanistic data in support of this hypothesis is currently missing." (PMID 36674511, 2023). "High-throughput sequencing data indicated that KAT2A deficiency could downregulate a series of cancer-associated crosstalk, and the top hit was glycolysis." (PMID 34268311, 2021). "We focused on the lysine acetyltransferase 2A (KAT2A) since it is important in multiple cancer indications with a clinical inhibitor in development." (PMID 41826695, 2026). "As demonstrated by pan-cancer analysis, KAT2A expression is significantly upregulated in multiple cancer types." (PMID 41225436, 2025). "We first examined KAT2A expression patterns across multiple cancer types using the TIMER2.0 database." (PMID 41225436, 2025). "Lysine acetyltransferase 2 A (KAT2A) plays a pivotal role in epigenetic gene regulation across various types of cancer." (PMID 40140561, 2025). "Conversely, decreasing KAT2A expression can significantly reduce the proliferation and migration of cancer cells and the growth of xenograft tumors." (PMID 39735192, 2024). "The upregulated genes were associated with extracellular matrix remodeling and cancer pathways, including LAMC1-3, COL9A2, COL1A1, MYL9, MYH11, and KAT2A." (PMID 39735192, 2024). "Overall, pY-SREBF1/H2A-K130ac signaling explains cancer sex bias and reveal synchronous inhibition of KAT2A and Tyr-kinases as an effective therapeutic strategy." (PMID 37296155, 2023). "Metastasizing cancer cells rely on CPT1a-dependent palmitate oxidation to acetyl-CoA, which in turn serves as a substrate for the acetylation of p65 by KAT2a." (PMID 36732635, 2023). "KAT2A contributes to cancer through the control of transcriptional activity, mainly the co-activation of E2F and Myc transcriptional targets." (PMID 36674511, 2023). "MYC family of transcription factors are associated with several epigenetic regulators during development and cancer, including KAT2A (also known as GCN5)." (PMID 37777587, 2023). "We used qRT-PCR to compare KAT2A expression in cancer and adjacent tissues and among different cell lines." (PMID 38058677, 2023). "Several studies have demonstrated that KAT2A functions as an epigenetic oncogene in several cancers." (PMID 37789275, 2023). "The downregulation of KAT2A can significantly reduce the proliferation and migration of cancer cells and the growth of xenograft tumors." (PMID 36292703, 2022). "In this study, we found that KAT2A was generally highly expressed in seven cancer tissues compared with normal tissues, including BLCA, CHOL, ESCA, and HNSC, KIRP, STAD, and THCA." (PMID 36292703, 2022). "This study analyzed The Cancer Genome Atlas (TCGA) to screen potential candidate genes and the regulation network of KAT2A and E2F1 complex in pan-cancer." (PMID 36292703, 2022). "Our data show that the KAT2A has higher expression in 9 cancer types which indicates the increased histone acetylation level in specific gene promoters among these cancers to be involved in the development of cancer." (PMID 31828117, 2019).
cancer (continued). "Further study is needed to investigate ACLY, SLC2A1, and KAT2A in the histone acetylation function across cancer types." (PMID 31828117, 2019). "Kat2a and Kat2b regulate various physiological phenomenon, including embryonic development, brown adipogenesis, transcription, genome stability, cancer, immune response, and angiogenesis." (PMID 30424580, 2018). "The top-scoring genes recurring in the four gene sets included key cancer genes, KAT2A, SKP1, FZD1, JAG1 and PSEN2." (PMID 28473661, 2017). "Notably, KAT2A expression was detected across all identified cell clusters, encompassing normal epithelial cells, cancer cells, endothelial cells, fibroblasts, lymphocytes, myeloid cells, and plasma cells." (PMID 41225436, 2025). "This apparent discrepancy may be explained by taking into consideration that KAT2A catalyzes acetylation not only of the histone H3 tails, but of many other proteins, and the role of KAT2A in cancer is still under debate." (PMID 40743051, 2025). "A pan-cancer study indicated that KAT2A was found to cooperate with E2F1 and be recruited by E2F1 to the UBE2C promoter for elevating the expression of UBE2C by increasing the acetylation level of H3K9 to promote cell proliferation and the migration of cancer cells." (PMID 39546499, 2024). "Prior studies have interrogated the function of KAT2A in MYC-driven cancer." (PMID 38820154, 2024). "This indicates that KAT2A might be more important in cancer cells than under physiological conditions." (PMID 38213532, 2023). "Recent studies demonstrated the significant contribution of KAT2A to cancer progression." (PMID 36674511, 2023). "By screening the transcriptome data of 11 cancer tissues of TCGA, it was exposed that the gene set potentially co-regulated by KAT2A and E2F1 was significantly enriched in the cell cycle, and participated in DNA replication, base excision repair, and nucleotide excision repair." (PMID 36292703, 2022). "Particularly, KAT2A was significantly upregulated in all five types of cancer (p = 0.028)." (PMID 35422864, 2022). "Although PVT1 has been shown to regulate HIF1α transcriptionally by binding with KAT2A and play oncogenic roles in cancers, we demonstrated that PVT1 could bind HIF2α and stabilize HIF2α protein, thus promote tumorigenesis and angiogenesis." (PMID 34321604, 2021). "The lysine acetylation regulators with CNV amplification showed significantly higher expression in cancer cells when compared to normal cells (e.g. KAT2A and ATAT1), while the regulators with CNV deletion showed significantly lower expression (e.g. SIRT6 and SIRT7)." (PMID 34136387, 2021). "As expected, the results of our data show that the KAT2A gene has high expression in 9 cancer types, and it may be explained that KAT2A is important for controlling the gene expression program for adjusting histone acetylation in these cancer types." (PMID 31828117, 2019). "Importantly, KAT2A has been shown to be significantly upregulated in many cancers, including CRC, and has been associated with promoting more aggressive phenotypes and progression in different cancer entities." (PMID 40140561, 2025). "Thus, we hypothesize that KAT2A may serve as a promising target with effective therapeutic prospects for various cancer types." (PMID 40140561, 2025). "Thus, similar approaches could be envisioned for KAT2A where the nuclear translocation of -KGDH is potentially a consequence of cancer and enhanced glycolysis." (PMID 38213532, 2023). "Therefore, KAT2A may be a significant oncological target with effective therapeutics for several cancers." (PMID 36292703, 2022). "Recent studies illustrate that desuccinylase (e.g., SIRT5 and SIRT7) and succinyltransferase (e.g., KAT2A, CPT1A, HAT1, and alpha-KGDH) expression and malfunction are strongly related to immune escape of cancer." (PMID 40865948, 2025).
cancer (continued). "Acetyltransferase such as KAT2A is found to be involved in oncogenesis, and it is responsible for acetylating H3K9, along with other non‐histone acetylations that contribute to cancer progression." (PMID 40159638, 2025). "The top enriched pathways for the upregulated genes included focal adhesion, regulation of actin cytoskeleton and pathway in cancer, as well as the key upregulated genes included LAMC1, MYL9, COL1A, and KAT2A which, regulate ECM formation and actin skeleton." (PMID 39735192, 2024). "Conversely, HDAC1, HDAC10, KAT2A, SIRT6, and SIRT7 were upregulated in 13, 16, 17, 14, and 12 cancer types." (PMID 39906742, 2024). "In our previous study, we found that UBE2C was co-regulated by lysine acetyltransferase 2A (KAT2A) and E2F transcription factor 1 (E2F1) to promote cell proliferation and migration in pan-cancer." (PMID 37958642, 2023). "In a variety of types of malignant tumors, there is a consistent over-expression of multiple BCPs genes on which tumors depend, including BRD2, BRD4, ATAD2, KAT2A, etc.." (PMID 37142850, 2023). "Furthermore, it is worth mentioning that HAT1 and KAT2A were highly expressed in advanced TNM stages, suggesting the expression of these signature genes may be associated with advanced-stage and high-grade carcinomas of LIHC." (PMID 37763801, 2023). "From the GEPIA online analysis, we found that compared with the expression level distributed in a normal person, KAT2A was slightly higher in cancer patients, and E2F1 was obviously higher expressed in cancer patients." (PMID 36292703, 2022). "Both the expression levels of KAT2A and E2F1 were significantly up-regulated in the same 16 cancers, and E2F1 was also higher expressed in CESC, GBM, KICH, and UCEC cancers." (PMID 36292703, 2022). "Given the clinical and functional significance of KAT2A/E2F1/UBE2C in pan-cancer, we concluded that KAT2A/E2F1/UBE2C and its associated pathway were crucial for cancer carcinogenesis, and targeting this pathway may be pivotal in the prevention or treatment of pan-cancer." (PMID 36292703, 2022). "Taken together, these reports indicated that KAT2A, E2F1, and UBE2C play a fundamental role in the progression of several types of cancers." (PMID 36292703, 2022). "In this study, we performed a comprehensive pan-cancer analysis on four well-known succinylation regulators (CPT1A, KAT2A, SIRT5, and SIRT7)." (PMID 33681201, 2021). "Firstly, we inquired about the KAT2A expression levels from the Cancer Cell Line Encyclopedia (CCLE) dataset and selected two KAT2Ahigh cell lines (Caki-2 and A498) for the following studies, in which KAT2A was preferentially expressed." (PMID 34268311, 2021). "ACLY, SLC2A1, KAT2A, and DNMT3B are the critical genes contributing to epigenetic dysfunction across cancers." (PMID 31828117, 2019). "Our research clarifies some key metabolic genes, ACLY, SLC2A1, KAT2A, and DNMT3B, which are most disordered and indirectly contribute to the dysfunction of histone acetylation and DNA methylation in cancer." (PMID 31828117, 2019). "Considering the analysis results of the transcriptional data of various cancers in the TCGA database, it is suggested that UBE2C may be a downstream gene that is co-regulated by KAT2A and E2F1." (PMID 36292703, 2022). "This study revealed the common characteristics of KAT2A/E2F1/UBE2C and clarified the mechanism of this axis across pan-cancer through RNA-seq dada and in vitro experiments, which might shed light on pan-cancer treatment." (PMID 36292703, 2022). "KAT2A, the first discovered KAT that was related to transcription, has been reported to be involved in gene transcription, DNA repair, nucleosome assembly, and cell cycle regulation in pan-cancer." (PMID 36292703, 2022). "With such conspicuous roles of both KAT2A and E2F1 in cellular functions and putative links to cancer, we investigated the common molecular mechanisms and potential transcription target of their interaction across pan-cancer." (PMID 36292703, 2022).
cancer (continued). "In addition, the expression levels of KAT2A and E2F1 in pathological stages were remarkably higher expressed in stage III and IV in 10 cancers." (PMID 36292703, 2022). "It was suggested that the regulatory network of KAT2A and E2F1 involved in the cancer process was very complex, and it could regulate the expression level of genes involved in the cancer development process." (PMID 36292703, 2022). "KAT2A, a member of the GCN5-related N-acetyltransferase (GNAT) family of KATs, has been reported to be abnormally expressed and to play an essential role in the progression of various types of cancer." (PMID 34381019, 2021). "KAT2a inhibition did not decrease proliferation of cancer cells growing in 2D." (PMID 36732635, 2023). "Moreover, KAT2A and E2F1 could promote cell proliferation and the migration of cancer cells by enhancing the expression of UBE2C." (PMID 36292703, 2022). "KAT2A has also been shown to play a critical role in carcinogenesis and the progression of several cancers; however, there are no reports of the impact of KAT2A on the non-histone acetylation of AR, and its potential role in primary or secondary resistance to abiraterone." (PMID 34381019, 2021). "In addition to H3K9 acetylation, both Kat2a and Kat2b acetylate other non-histone substrates in various aspects of development and disease, including brain development and cancer." (PMID 30424580, 2018). "Hitherto, no conclusive study has reported the role of KAT2A and E2F1 interactions in the pan-cancer landscape." (PMID 36292703, 2022). "Next, we asked if our observation that KAT2A restricts ADAM12 expression, made in a non-transformed cell context, was also relevant in cancer." (PMID 30753595, 2019). "Using cellular systems, an animal model, and bioinformatics, we find that a non-canonical but druggable TGF-β/KAT2A/TAK1 axis controls ADAM12 induction in normal and cancer cells." (PMID 30753595, 2019).